RNU6-1206P (RNA, U6 small nuclear 1206, pseudogene)
Gene: Small nuclear RNA gene on chromosome 2 (201,079,842 to 201,079,944, forward strand). Ensembl gene ENSG00000252148.
Homologues: Orthologues: chimpanzee U6 (100% identical), macaque U6 (64% identical), pig U6 (58% identical), mouse Gm24676 (54% identical). Paralogues in human: RNU6-1020P (80% identical), RNU6-1251P (80% identical), RNU6-348P (80% identical), RNU6-1011P (79% identical), RNU6-1060P (79% identical), RNU6-106P (79% identical), RNU6-1124P (79% identical), RNU6-1181P (79% identical), RNU6-12P (79% identical), RNU6-13P (79% identical), RNU6-16P (79% identical), RNU6-19P (79% identical), and 1285 more.